KRAS (KRas proto-oncogene, GTPase)
Diseases named in the same sentence as KRAS in open-access papers (continued):
Sharing a sentence is not in itself a finding about the gene and the disease.
colorectal cancer (continued). "Moreover, a significant relationship (p < 0.05) was identified between the KRAS gene status in gastric and colorectal cancer and that of the control group in tissue samples." (PMID 39673361, 2024). "The meta-analysis supports the use of EGFR mAbs in the treatment of mCRC without mutations in KRAS, particularly for left-sided colorectal cancer and where the tumour does not harbour NRAS or BRAF mutations." (PMID 38402342, 2024). "Colorectal cancer (CRC) responses to KRAS-targeted inhibition have been limited due to low response rates, the mechanisms of which remain unknown." (PMID 39061234, 2024). "The KRAS G12C mutation, a specific alteration in the KRAS gene, has been identified in a variety of malignancies, including non-small cell lung cancer (NSCLC) and colorectal cancer (CRC)." (PMID 39518114, 2024). "However, a study conducted in colorectal cancer demonstrated that the CCDC6::RET fusion is mutually exclusive with other important driver mutations, such as KRAS, BRAF and PIK3CA." (PMID 39684377, 2024). "However, CDX2-suppressed colorectal cancers had a higher prevalence of mutations in alternative genes of the WNT/APC/β-catenin and KRAS/BRAF/MEK pathways." (PMID 39452477, 2024). "Since KRAS mutations occur frequently in colorectal cancer, we asked whether SLUG&P4HA2 overexpression may contribute to poor prognosis in KRAS mutated CRC." (PMID 38522060, 2024). "KRAS may also play a role in modulating the tumor microenvironment to promote tumor progression as seen in preclinical studies in colorectal cancer." (PMID 39337530, 2024). "iii) Conduct clinical trials on KRAS-mutant patients: FOLFIRI plus cetuximab may be the first-line regimen for patients with KRAS exon 2 wild-type colorectal cancer, according to a phase III clinical trial." (PMID 38706597, 2024). "Besides, Combined inhibition of both MEK and CDK4/6 is effective in preclinical models of KRAS mutant CRC (Colorectal Cancer) and justifies a planned phase II clinical trial in patients with refractory KRAS-mutant CRC27." (PMID 38600093, 2024). "In colorectal cancer (CRC), NRAS mutations are rare compared to KRAS, but may lead to worse outcomes." (PMID 39451209, 2024). "However, clinical data shows that the most frequent outcome of KRAS-targeted inhibition in colorectal cancer is stable disease, indicating that cancer cells are indeed sensitive to KRAS inhibition to the point of stalling their growth rate." (PMID 39061234, 2024). "Similarly, cetuximab treatment facilitates RSL3-induced ferroptosis through the inhibition of NRF2/HO-1 signaling in KRAS-mutant colorectal cancer cells." (PMID 38424190, 2024). "Notably, other KRAS alleles such as KRASG12S and KRASG13D are mainly restricted to colorectal cancer." (PMID 38684865, 2024). "In addition to cancer-testis antigens, mutations in genes such as KRAS have emerged as promising targets for TCR-T therapies, particularly in cancers such as pancreatic and colorectal cancers (NCT03190941)." (PMID 39439803, 2024). "Mutant KRAS was identified as a key driver of tumor immune evasion in colorectal cancer." (PMID 38338768, 2024). "Another Chinese study on stage IV colorectal cancer patients found that the presence of KRAS mutation and the primary tumor location did not influence the efficacy of bevacizumab-containing chemotherapy." (PMID 39335752, 2024).
colorectal cancer (continued). "A study of the proteome of the intermediate-stage colorectal cancer cell line Caco2 revealed that the mutant KRAS (V12) contributed to an increased H-Ras protein level, indicating that HRAS might be a pivotal factor involved in the effects of KRAS mutation." (PMID 38481800, 2024). "In colorectal cancer, KRAS, NRAS, BRAF, and PIK3CA mutations induce a negative effect on the response to anti-EGFR therapies." (PMID 38248103, 2024). "Additionally, mutational variants of EGFR, KRAS, and PIK3CA genes are identified by CTCs sequencing in patients with colorectal cancer, which are associated with therapeutic response to EGFR-targeted therapy in patients." (PMID 40026568, 2024). "Simtuzumab has shown limited efficacy in patients with pancreatic cancer or KRAS-mutant colorectal cancer, which may be due to the indirect and weak blocking effect of simtuzumab on the interaction of LOXL2 with PEAR1." (PMID 39145451, 2024). "Mutated genes common to both lung and colorectal cancers include BRAF and KRAS." (PMID 38770671, 2024). "MTX-211 (also known as Mol 211, HY-107364), functioning as a dual inhibitor targeting both epidermal growth factor receptor (EGFR) and phosphoinositide-3 kinase (PI3K), exhibited potent in vivo growth-inhibitory effects against colorectal cancer models characterized by BRAF and KRAS mutations." (PMID 38791198, 2024). "Furthermore, even within KRAS G12C–mutant tumors, there are notable differences in the mechanisms of resistance to KRAS G12C inhibitors between non–small cell lung cancer and colorectal cancer." (PMID 39704172, 2024). "We identified this complex in every PDX sample evaluated, including PDXs from lung, pancreatic and colorectal cancers with mutant KRAS, mutant HRAS or mutant NRAS and from the HBEC line as well as from the WI-38 nonimmortalized nontransformed human lung fibroblast line." (PMID 39528835, 2024). "While the guidelines on colorectal carcinoma management recommend KRAS and BRAF V600E mutation analysis, this is not routinely performed in our country." (PMID 39364024, 2024). "According to the guideline by the American Society for Clinical Pathology, College of American Pathologists, Association for Molecular Pathology, and American Society of Clinical Oncology on biomarker evaluation in colorectal carcinoma, evaluation of mutation in BRAF and KRAS genes is recommended." (PMID 39364024, 2024). "In colorectal cancer, regardless of the presence or absence of KRAS mutations, glutamine is absorbed into the cell to produce fatty acids, proteins, and nucleic acids essential for cell survival and growth." (PMID 37371800, 2023). "The KRAS oncogene is a prognostic factor in patients with colorectal cancer." (PMID 37626641, 2023). "On the other hand, increasing Fn copy number in tissues was associated with increased probability to exhibit MSI-H, MLH1 hypermethylation or BRAF mutations but not KRAS mutations in colorectal cancer." (PMID 37772997, 2023).
colorectal cancer (continued). "KRAS activating mutations are considered the most frequent oncogenic drivers and are correlated with radio-resistance in multiple cancers including non-small cell lung cancer (NSCLC) and colorectal cancer." (PMID 37907934, 2023). "Together with the colorectal cancer data presented here, the association of genetic alterations including MSI-H, BRAF mutation, and KRAS mutations or MLH1 hypermethylation with Fn infection may be established during and/or after adenomacarcinoma transition." (PMID 37772997, 2023). "Because KRAS mutations are known to make EGFR inhibitors less effective, KRAS mutations have been tested as a negative selection to predict response to EGFR TKIs in colorectal cancer patients." (PMID 36810451, 2023). "KRAS, NRAS, BRAF V600E Mutations, DNA Mismatch Repair Deficiency/Microsatellite Instability Status, HER2 Amplification, and NTRK Fusions are NCCN approved and actionable molecular biomarkers for colorectal cancer." (PMID 36980565, 2023). "Emerging evidence shows that KRAS-mutant colorectal cancer (CRC) depends on glutamine (Gln) for survival and progression, indicating that targeting Gln metabolism may be a promising therapeutic strategy for KRAS-mutant CRC." (PMID 37937641, 2023). "Low ERH expression was associated with better survival of colorectal cancer and lung cancer patients with tumors harboring KRAS mutations (though not significantly in the latter patients)." (PMID 37887293, 2023). "In addition, there is a report that NF-KB activation is involved in KRAS mutant colorectal cancer, with NF-kB activity being higher than it is in wild-type KRAS colorectal cancer." (PMID 37758931, 2023). "Here, mutant KRAS is identified as a key driver of tumor immune evasion in colorectal cancer (CRC)." (PMID 36599679, 2023). "Notably, CIMP colorectal cancer is associated with BRAF V600E and KRAS mutations, CDX2 loss, as well as low chromosomal aberrations and high microsatellite instability (MSI), which is reported to be driven by methylation of hMLH1 gene." (PMID 37234978, 2023). "Moreover, a reverse genetic screen study has demonstrated that reduction of reactivated CRAF induced by MEK1/2 inhibitors enlarges the clinical benefit of the latter in KRAS mutant colorectal cancer (CRC) cell lines." (PMID 36872366, 2023). "In addition, in a KRAS metastatic colorectal cancer model, PI3K inhibitor BKM120 resulted in decreased tumor volume." (PMID 37154160, 2023). "For instance, the inhibition of Glut2 (Slc2a2) dynamics has the potential to improve diabetes mellitus in mice, and Slc7A5, a glutamine antiporter, could be an attractive target for therapy-resistant, KRAS-mutant colorectal cancer in mice." (PMID 36787192, 2023). "In KRAS colorectal cancer cells, KRAS and Ago2 participate in targeting miRNAs to exosomes." (PMID 36674857, 2023). "It has also reported that statins use did not improve progression free survival and OS in KRAS-mutated colorectal cancer patients treated with XELOX + bevacizumab with/without cetuximab." (PMID 37069612, 2023). "There is currently no reason to believe that patients affected by KRAS-mutated colorectal cancer have lower sensitivity to radiotherapy treatment than those in the wild-type category." (PMID 36836752, 2023). "Limitations of this study include that it does not confirm whether statins have an antitumor effect or L-OHP-induced peripheral neuropathy in clinical practice in patients with KRAS-mutant colorectal cancer." (PMID 37069612, 2023). "Strikingly, T cells and/or B cells are required for durable responses to KRAS inhibitors in mouse models of lung cancer, colorectal cancer, and PDAC, suggesting that the priming of an adaptive immune response may efficiently eliminate drug resistant cells." (PMID 37581538, 2023).
colorectal cancer (continued). "For example, ISGylation could regulate the stability of KRAS or β-catenin and maintain the malignant phenotypes of breast cancer and colorectal cancer." (PMID 37501099, 2023). "Compared with colorectal cancer without KRAS mutations (non-KRAS mutated-CRC), a significantly higher percentage of cases were infected with Fn (OR: 1.74, P = 0.02)." (PMID 37772997, 2023). "NOP56 is significantly increased in KRAS-mutant non-small cell lung cancer, KRAS-mutant pancreatic cancer, KRAS-mutant colorectal cancer, Wilms tumor, diffuse large B-cell lymphoma, Myc-mutant Burkitt’s lymphoma, breast cancer, prostate cancer, and acute lymphoblastic leukemia." (PMID 36741964, 2023). "Furthermore, TNTs were shown to transport mutant forms of KRAS to induce ERK signaling in colorectal cancer cells and multidrug resistance P-glycoprotein in multiple cancer types." (PMID 37249209, 2023). "In the present study, expression of CERS4 was reduced in KRAS mutant colorectal cancer." (PMID 37758931, 2023). "We further report 81 candidate KRAS-reactive TCRβs from two patients with colorectal cancer." (PMID 37776855, 2023). "Reports from Taiwan of KRAS wild-type colorectal cancer refractory to two or three regimens and from Italy of RAS/BRAF wild-type colorectal cancer refractory to two or three regimens both suggested that the therapeutic effect of anti-EGFR antibodies is better in left-sided colorectal cancer." (PMID 37760533, 2023). "Therefore, the detection and evaluation of the KRAS gene is an important tool for the early diagnosis and treatment of colorectal cancer." (PMID 37008032, 2023). "Downregulation of NOP56 expression significantly inhibited the proliferation of KRAS mutant lung, pancreatic and colorectal cancer cells, and NOP56 mRNA levels have been suggested to be a predictive marker of rapamycin sensitivity (IC50) in KRAS mutant cancers." (PMID 36741964, 2023). "Two examples can be considered: the lack of response to imatinib in non-GIST c-kit mutated tumors and the biochemistry of KRAS p.G12C mutations in colorectal cancer." (PMID 37759584, 2023). "In a study performed on colorectal cancer, 63 radiomic features were extracted from FDG PET/CT images, and the results revealed that the 25th percentile of SUVmax was the independent risk factor for KRAS mutation." (PMID 37509345, 2023). "In addition, the investigation of glutamine metabolism as a therapeutic approach for KRAS-mutant colorectal cancer (CRC) has advanced significantly." (PMID 37689664, 2023). "KRAS is an important tumor intrinsic factor driving immune suppression in colorectal cancer (CRC)." (PMID 37542037, 2023). "In a study by Flanagan, the Fn load between colorectal cancer with KRAS mutations and those with non-KRAS mutations, as well as colorectal cancer with BRAF mutations and those with non-KRAS mutations were compared." (PMID 37772997, 2023). "KRAS mutations have also been reported to have a negative impact on patients with colorectal cancer." (PMID 36675641, 2023). "A recent study reported that RGL2 could drive the metastatic progression of colorectal cancer via preventing the degradation of β-Catenin and KRAS." (PMID 37237274, 2023). "Furthermore, colorectal cancer is a highly heterogeneous clinical entity; genetic KRAS, NRAS, BRAF, or HER2 genes also work as the critical diagnostic and prognostic biomarkers." (PMID 36831695, 2023). "This fundamental step forward has stimulated scientific research on other potential targets of KRAS, both indirect and direct, and combination treatments aiming to overcome the mechanisms of resistance to these drugs that decrease in efficacy in colorectal cancer." (PMID 36836752, 2023).
colorectal cancer (continued). "It has been reported that colorectal cancer patients with mutated KRAS suffer from more lung metastasis but not liver or peritoneal metastasis." (PMID 38087207, 2023). "The objective of this study is to investigate the potential of radiomic features derived from multi-parametric MRI scans, which includes both morphological and functional imaging, in predicting the KRAS mutation status, tumor staging, and EMVI in patients with colorectal cancer." (PMID 38066782, 2023). "In colorectal cancer (CRC), the proliferation of KRAS-mutated cancer cell rely on ARID1A." (PMID 37727377, 2023). "EGFR inhibitor cetuximab can be used as a superior chemotherapy drug for advanced colorectal cancer patients without KRAS mutation." (PMID 37777749, 2023). "G12D is the most prevalent KRAS mutation in pancreatic cancer and colorectal cancer, however, the aspartic acid mutation does not render the same chemical reactivity as the cysteine mutation." (PMID 37221195, 2023). "Understanding the correlations between the demographic, clinical, and paraclinical variables and the outcomes in mCRC patients with KRAS-mutant and KRAS wild-type colorectal cancer is essential for improving patient care and treatment strategies in Romania and beyond." (PMID 37761297, 2023). "In colorectal carcinoma, WDR76 could degrade pan-RAS and inhibit cancer stem cell activation, as well as the progression of colorectal carcinoma cell cycle by degrading KRAS, thereby damaging the tumor development." (PMID 37081180, 2023). "For enterovirus group B, coxsackievirus B3 Nancy strain showed an oncolytic activity in xenografted mouse models of NSCLC, small cell lung cancer, KRAS-mutant lung adenocarcinomas, and colorectal carcinomas by specific receptors on cancer cell, including CAR, DAF, and heparan sulfates (HS)." (PMID 37743418, 2023). "Besides, dual-specificity tyrosine-(Y)-phosphorylation regulates kinase 2 (DYRK2) and miR-622 inhibit the invasion and migration of colorectal cancer cells by targeting the Kirsten rat sarcoma viral oncogene homolog (KRAS)." (PMID 35872695, 2022). "Growing studies have revealed that miR-145 and miR-143 could target the KRAS gene in colorectal cancer." (PMID 35330456, 2022). "Targeting the KRAS pathway is a promising but challenging approach for colorectal cancer therapy." (PMID 34718347, 2022). "Cologuard tests the stool samples provided by the tester and uses the multi-target detection method to analyze the protein and DNA biomarkers related to colorectal cancer and precancerous lesions, mainly including hemoglobin FIT, and DNA site mutation (KRAS gene), DNA methylation." (PMID 36119474, 2022). "Colorectal cancer is known to often develop through a specific number of events along the so‐called conventional pathway, which is a multistep process initiated by mutations in APC, KRAS or BRAF genes." (PMID 35383926, 2022). "Similarly, furin has been identified as a pro-oncogenic driver of KRAS and/or BRAF-mediated ERK kinase-pathway activation, which has been linked to the resistance of colorectal cancer to targeted therapies." (PMID 35406405, 2022).